IL6 (interleukin 6)
Diseases named in the same sentence as IL6 in open-access papers (continued):
Sharing a sentence is not in itself a finding about the gene and the disease.
myopic macular degeneration (2 papers, 2024 to 2025). "Further analysis showed that IL-6 and MCP-1 were able to predict myopic macular degeneration with AUC of 0.783 and 0.682, respectively." (PMID 39597899, 2024).
necrosis (2 papers, 2022). The phenotypic observation that death has occurred in groups of cells or in one or more tissues due to external factors, such as infection, toxins, mechanical trauma, loss of blood supply and other injuries (e.g. corrosion or burning). "Lately, an association between circulating IL-6 levels and the extent of myocardial necrosis has been described in a large cohort of 1028 STEMI patients." (PMID 35204357, 2022). "In accordance with our study, clinical studies have represented a correlation between the area of myocardial necrosis and the plasma IL-6 levels in patients with AMI." (PMID 36091399, 2022).
Newcastle disease (2 papers, 2024 to 2025). A condition caused by infection by the Newcastle disease virus, which may be characterized by conjunctivitis, respiratory illness, and diarrhea. "Studies have found that IL-6 is involved in the innate immunity of poultry diseases such as Newcastle disease (ND)." (PMID 39965774, 2025).
nonalcoholic fatty liver (2 papers, 2019 to 2020). "TNF-α and IL-6 inhibit the expression of adiponectin and promotes the inflammatory response of nonalcoholic fatty liver." (PMID 31717842, 2019).
oculopharyngeal muscular dystrophy (2 papers, 2022 to 2025). Oculopharyngeal muscular dystrophy (OPMD) is an adult-onset progressive myopathy characterized by progressive eyelid ptosis, dysphagia, dysarthria and proximal limb weakness. "In addition, let-7-targeting paired cassette 7 (PAX7) and IL-6 in senescent muscle and oculopharyngeal muscular dystrophy (OPMD), a disease that shares molecular characteristics with senescent muscle, leads to reduced muscle regeneration and functional degeneration." (PMID 36008964, 2022).
opioid use disorder (2 papers, 2025). A substance-related disorder that involves the recurring use of opioids despite negative consequences. "The randomized, double-blind, sham-controlled clinical trial investigated the effects of bilateral tDCS on craving, tumor necrosis factor-alpha (TNF-a) and interleukin-6 (IL-6) expression levels, and impulsivity in adult males with opioid use disorder (OUD)." (PMID 40725591, 2025). "Nonetheless, other studies indicate that in patients with opioid use disorder, an analysis of memory ability shows a negative correlation with TNF-α and IL-6 levels." (PMID 39857699, 2025).
oral candidiasis (2 papers, 2012 to 2023). Infection of the mucosal lining of the mouth with the fungus Candida albicans. "Thus, it is suggested that AC-PACs by interfering in signal transduction cascade may contribute to reduce the impact of host inflammatory processes mediated by elevated production of IL-6 and IL-8 occurring in oral candidiasis." (PMID 22248145, 2012).
pancreatic NENs (2 papers, 2021 to 2023). "The tumour-derived cytokine IL-6, which is associated with high circulating levels of CRP, have been shown to be prognostic in pancreatic NENs, lending support to a CRP-based inflammatory score in NENs." (PMID 34439386, 2021).
pancreatic NET (2 papers, 2020 to 2025). "Our experiments in BON-1 cells derived from a pancreatic NET revealed significant treatment-related increase in TNFα synthesis paralleled by a significant reduction in IL-6 and IL-10 expression; this cytokine profile reflects the ability of lanreotide to induce a Th1 cytotoxic immune-response." (PMID 32766136, 2020).
parathyroid adenoma (2 papers, 2022 to 2025). "Subgroup analysis revealed that the increases in IL-6 and ESR were statistically significant in both parathyroid adenoma and multiglandular disease cases." (PMID 40529359, 2025).
pasteurellosis (2 papers, 2020 to 2021). Infections with bacteria of the genus pasteurella. "In lambs naturally infected with pneumonic pasteurellosis, the association between measured proinflammatory cytokines and clinical sum score demonstrated a positive correlation with interleukin-6 and interferon gamma." (PMID 34944151, 2021). "The correlation between assessed proinflammatory cytokines and CIIS in lambs naturally infected by pneumonic pasteurellosis revealed a positive correlation between CIIS and IL-6 and IFNγ, while other estimated proinflammatory cytokines exhibited a negative correlation with CIIS." (PMID 34944151, 2021). "Therefore, in this study we have investigated the impact of vitamin C on the production of pro-inflammatory cytokines (IL-1β, IL-6, IL-12p40, IFN-γ, and TNF-α) in lambs naturally infected by pneumonic pasteurellosis." (PMID 34944151, 2021). "Wilks’ lambda test for drug × time interaction, p < 0.0001) of vitamin C, a major water-soluble vitamin in normalization the pro-inflammatory cytokines (IL-1β, Il-6, IFN-γ, and TNF-α) when used in combination with tulathromycin in lambs with pneumonic pasteurellosis." (PMID 34944151, 2021).
peripheral nerve lesion (2 papers, 2015 to 2016). "During the repair phase following peripheral nerve lesion, dedifferentiated Schwann cells secrete a variety of neurotrophic factors and cytokines including NGF, BDNF, NT-4/5, FGF-2, IGF-1, IL-6, and IL-1ß that support neuronal survival and regenerative growth of axons." (PMID 26635533, 2015).
peritoneal mesothelioma (2 papers, 2014 to 2024). A benign or malignant mesothelial neoplasm that arises from the peritoneum. "The enrichment of cytokine signalling underscores the potential impact of inflammation, particularly the positive regulation of interleukin-6 (IL-6) production, on the progression of peritoneal mesothelioma." (PMID 39516360, 2024).
personality disorder (2 papers, 2022 to 2023). A diverse category of psychiatric disorders characterized by behavior that deviates markedly from the expectations of the individual's culture; this pattern of deviation is pervasive and inflexible and is stable over time. "The second study found that in a sample of 34-year-olds with and without personality disorders, retrospective reports of parental psychological control were positively correlated with IL-6 and CRP concentrations, independent of personality disorder diagnosis." (PMID 34347228, 2023).
phlebitis (2 papers, 2018 to 2023). Inflammation of a vein. "Mirabilite can significantly reduce the expression levels of interleukin (IL)-1, IL-6, and tumor necrosis factor-α (TNF-α) in mechanical phlebitis caused by a venous indwelling needle, and reduce the inflammatory response in rabbit ear vein." (PMID 37532999, 2023). "The phlebitis ointment reduced the levels of necrosis factor-α, interleukin-6, C-reactive protein, and interleukin-1ß." (PMID 29849699, 2018). "In conclusion it can be stated that the phlebitis ointment reduced the levels of necrosis factor-α, interleukin-6, C-reactive protein, and interleukin-1ß." (PMID 29849699, 2018).
pleural empyema (2 papers, 2012 to 2022). The presence of pus in the thoracic cavity, between the visceral and parietal pleura. "In our case, IL-6 inhibitor is considered one of causes diagnosed after reaching pleural empyema." (PMID 35389108, 2022).
Pleuritis (2 papers, 2023 to 2025). Inflammation of the pleura. "Amongst the TB pleuritis patients, IL-6 and CXCL13 had the highest fold decline as compared to the baseline levels." (PMID 36635313, 2023).
pneumonic plague (2 papers, 2022 to 2023). A plague in which the bacteria have infected the lungs. "Using an i.n. murine infection model of pneumonic plague, we found that partially alleviating early suppression of host responses by deleting Pla resulted in increased expression of host IL-6, MCP-1, and IL-17 during the early preinflammatory phase of disease." (PMID 37338372, 2023).
pneumothorax (2 papers, 2020 to 2022). Abnormal presence of air in the pleural cavity. "On the other hand, IL-1Ra, IL-6, MCP-1, and D-dimer levels were elevated in cases presenting with pneumothorax compared to normal cases or cases presenting with consolidation or ground-glass opacities." (PMID 35529862, 2022).
Pneumovirus Infections (2 papers, 2021 to 2023). Infections with viruses of the genus PNEUMOVIRUS, family PARAMYXOVIRIDAE. "IL-6−/− mice showed a significant reduction in neutrophil recruitment and lower mortality in the mouse model of acute pneumovirus infection." (PMID 38139043, 2023).
pouchitis (2 papers, 2023 to 2024). Acute inflammation in the intestinal mucosa of the continent ileal reservoir (or pouch) in patients who have undergone ileostomy and restorative proctocolectomy (proctocolectomy, restorative). "More recently, the administration of exogenous lysozyme to rats with pouchitis has shown pouchitis amelioration associated with decreased TNF-α and IL-6 in the pouch tissue." (PMID 39770958, 2024). "A cytokine storm (IL-1beta, IL-6, IL-8 and TNF-alpha), with the gain of function mutations in IL1β and the disruption of intestinal barrier, complete the picture of mucosal inflammation in pouchitis." (PMID 39770958, 2024). "Supplementation with exogenous lysozyme significantly ameliorated pouchitis, lowering the levels of inflammatory cytokines such as TNF-α and IL-6 in the pouch tissue." (PMID 38137976, 2023).
pregnancy disorder (2 papers, 2020 to 2021). A disorder that is related to pregnancy. "Women affected by pregnancy disorders exhibit an enhanced inflammatory state, as well as elevated levels of pro-inflammatory cytokines, such as TNF-α and IL-6, systemically and locally in the placenta." (PMID 32570911, 2020).
promyelocytic leukemia (2 papers, 2018 to 2020). "The human promyelocytic leukemia cell line HL-60 was differentiated along the macrophage/monocyte lineage, and LPS stimulation with either 0.1 μg/mL or 1 μg/mL LPS led to dose-dependent TNFα and IL-6 induction." (PMID 33233817, 2020). "To clarify the molecular mechanisms of the miR‐223/IL‐6 secretion pathway in human neutrophils after infection with S. aureus, we established a miR‐223 knockdown human promyelocytic leukemia HL‐60 cell line that could be differentiated to neutrophils upon treatment with DMSO using miR‐223 AS ODN." (PMID 30171089, 2018).
protozoal diseases (2 papers, 2021 to 2023). "Some studies have shown a remarkable elevation in IL-1β, IL-6, IFN-γ, and TNF-α cytokines in systemic protozoal diseases in cattle." (PMID 36679958, 2023). "IFN-γ, a cytokine critical for innate and adaptive immune responses against viral and protozoal infections, activates HMC3 to release pro-inflammatory cytokines, including TNF-α, IL-1β and IL-6, all of them are important transcriptional regulator of inflammasome pathways." (PMID 34106880, 2021).
prurigo nodularis (2 papers, 2021 to 2023). Prurigonodularis (PN) is a skin disease in which hard crusty lumps are formed on the skin that itches intensely. "More recently, this finding was supported by a positive relationship between pruritus severity and IL-6 in patients with prurigo nodularis." (PMID 36928456, 2023). "Higher serum levels of IL-6 have also been shown to correlate with higher itch levels in patients with prurigo nodularis, although the exact mechanism of IL-6-induced itch is not known." (PMID 35387042, 2021). "In addition, an increased amount of nerve fibers containing IL-6 was found in lesional compared to non-lesional skin of patients with the itchy skin diseases atopic dermatitis and prurigo nodularis." (PMID 36928456, 2023).
psittacosis (2 papers, 2022 to 2025). "We also noted the elevated expression level of IL6R in lymphocytes, suggesting that the IL-6/IL6R axis may be involved in psittacosis pathophysiology." (PMID 36119044, 2022).
pyonephrosis (2 papers, 2013 to 2024). "The chemokine CCL2/MCP-1 and the cytokine TGF-β have been frequently associated with urinary tract obstruction in patients with UPJO, whereas high urinary levels of IL-6 and of CXCL8/IL-8 were found in many patients with VUR and correlated to renal scarring and to renal function deterioration." (PMID 24066006, 2013).
R6 (2 papers, 2020 to 2025). "Notably, elevated levels of serum IL‐6, IL‐10, IL‐1β and IL12p70 and plasma IL‐6, TGF‐β1 and matrix metalloproteinase (MMP)‐9 were reported in the R6/2 HD mice." (PMID 38426291, 2025). "To test the hypothesis that IL-6 deficiency would be protective against the effects of mutant huntingtin, we generated R6/2 HD model mice that lacked IL-6." (PMID 32448329, 2020).
radiculitis (2 papers, 2018 to 2024). An inflammatory process affecting a nerve root. "Intrathecal injection of low-concentration O3 (10, 20, or 30 μg/mL) reduces the overexpression of TNF-ɑ, IL–6, and IL-1β and also significantly alleviates mechanical allodynia in chronic radiculitis rats." (PMID 30651902, 2018). "We speculate that intrathecal administration of low-concentration O3 diminishes radicular inflammation by reducing TNF-α, IL-1β, and IL-6 in radiculitis rats." (PMID 30651902, 2018). "Intrathecal administration of 10 μg/mL, 20 μg/mL, or 30 μg/mL oxygen/ozone significantly attenuated the decreased mechanical PWTs, downregulated the overexpression of spinal TNF-α, IL-1β, and IL-6, and increased the expression of cGMP and cAMP in chronic radiculitis rats." (PMID 30651902, 2018). "One study evaluated the intrathecal administration of low-dose ozone (10–30 μg/mL) in a model of chronic radiculitis, which led to a significant reduction in proinflammatory cytokines, such as TNF-α, IL-6, and IL-1β, and improved mechanical allodynia." (PMID 39598204, 2024).
renal adenocarcinoma (2 papers, 2020 to 2021). "We demonstrated that sunitinib increased IL-1β, IL-6,IL-8 and IL-18 expression in cardiomyocytes and renal adenocarcinoma cells and that polydatin is able to significantly reduce their expression." (PMID 34178667, 2021).
renal colic (2 papers, 2023 to 2024). A severe intermittent and spasmodic pain in the lower back radiating to the groin, scrotum, and labia which is most commonly caused by a kidney stone (RENAL CALCULUS) passing through the URETER or by other urinary track blockage. "CRP remains the most crucial clinical characteristic, followed by renal colic, HU value of effusion, G/A, IL-6, globulin, and PCT." (PMID 38896174, 2024). "The top 14 characteristics are arranged as shown: N/L, HU value of effusion, hemoglobin, renal colic, globulin, WBC, albumin, PCT, IL-6 and blood neutrophils." (PMID 38896174, 2024).
renovascular hypertension (2 papers, 2021 to 2024). High blood pressure secondary to renal artery stenosis. "Renovascular hypertension indicated an inflammatory process in the gastrointestinal tract, with increased levels of IL-1β and IL-6 and TNF-α in the duodenum." (PMID 34777003, 2021). "In the present study, we observed that renovascular hypertension increased the concentrations of IL-1β, IL-6, and TNF-α in the duodenum of 2K1C rats." (PMID 34777003, 2021). "In renovascular hypertensive rats, treatment ofolmesartan mitigates LVH and reduces IL-6 levels." (PMID 39076313, 2024).
Retinal atrophy (2 papers, 2017 to 2019). A nonspecific term denoting wasting, especially as a result of degeneration, of the retinal pigment epithelium (RPE) and neurosensory retinal cells. "None of the IL6 perturbations (IL6 KO, injection of anti-IL6Rα antibody or anti-gp130 antibody) caused retinal atrophy in the area of detachment (data of retinal thickness not shown)." (PMID 28645275, 2017).
Rett syndrome (2 papers, 2013 to 2025). A severe neurodevelopmental disorder affecting the central nervous system. "Recently, we have demonstrated that CNF1 can significantly decrease the levels of IL-1β in pure astrocytic cultures and the level of IL-6 in a mouse model of Rett's syndrome." (PMID 23738020, 2013).
Rickettsia infection (2 papers, 2015 to 2020). "Our present study suggests that severe rickettsioses are associated with endothelial pro-inflammatory cytokine production (IL-6 and IL-8), while less pathogenic rickettsial infection of endothelial cells correlates with increased levels of MCP-1." (PMID 26394396, 2015). "The first line of defense against Rickettsia infection is phagocytosis by macrophage, but Rickettsia is so-called macrophage-tropic bacteria, and interaction occurs during the phagocytosis, releasing IL-6 and IFN-γ from macrophage as an immune protection." (PMID 33322277, 2020).
right ventricular dilation (2 papers, 2022 to 2023). "IL-6 was only related to the presence of right ventricular dilation on the echocardiogram (p = 0.01)." (PMID 36014020, 2022).
ROSAH syndrome (2 papers, 2022 to 2025). "The current follow-up period under tocilizumab is still short (< 12 months), but the early anatomical response observed within one month suggests that IL-6 blockade may effectively suppress the underlying inflammatory component of ROSAH syndrome." (PMID 41269507, 2025). "Tocilizumab showed significant anatomical benefit in this ROSAH syndrome patient, suggesting a role for IL-6 in disease pathophysiology." (PMID 41269507, 2025). "This clinical case description adds to the growing body of evidence supporting the role of targeted therapies in managing ROSAH syndrome, offers insights into the broader implications of IL-6 blockade in autoinflammatory diseases, and helps expanding ROSAH phenotype." (PMID 41269507, 2025). "We also found that untreated patients with ROSAH syndrome had frequent elevations of CRP and proinflammatory plasma cytokines including TNF and IL-6." (PMID 35868845, 2022).
sensory impairment (2 papers, 2020 to 2022). "Secondly, more importantly, the expression of GFAP and inflammatory cytokines IL‐1β, IL‐6, and TNF‐α were increased both in PD patients with and without sensory impairment." (PMID 31828965, 2020).
Sensory neuropathy (2 papers, 2020 to 2022). Peripheral neuropathy affecting the sensory nerves. "In the context of chemotherapy-induced sensory neuropathy, pro-inflammatory cytokines such as interleukin-6 (IL-6) or tumor necrosis factor-α (TNF-α) appear to be of particular relevance." (PMID 31969555, 2020). "Thus, inhibiting the IL-6 pathway may result in synergistic effects by (a) augmenting antiproliferative effects and (b) prevention of sensory neuropathy with subsequent dose-alterations." (PMID 31969555, 2020). "The serum levels of IL-6 and IL-8 tended to be higher in patients with MPA with sensory neuropathy than in those without sensory neuropathy." (PMID 36362162, 2022). "The serum levels of IL-6 and IL-8 tended to be higher in patients with MPA with sensory neuropathy than in those without sensory neuropathy; however, this difference was not statistically significant (p = 0.19 and 0.12, respectively)." (PMID 36362162, 2022). "In addition, the serum levels of IL-6 and IL-8 in patients with MPA with sensory neuropathy tended to be higher than those in patients with MPA without sensory neuropathy." (PMID 36362162, 2022).
Sézary syndrome (2 papers, 2021 to 2025). "The results of the present study indicate that patients with Sheehan syndrome haveelevated levels of the inflammatory markers IL-6 and TNF-α compared withhealthy controls." (PMID 40741991, 2025). "Moreover, serum levels of IL-6 were demonstrated to correlate with tumor burden in Sézary syndrome and with clinical stage in non-leukemic CTCL." (PMID 32270320, 2021).
short bowel syndrome (2 papers, 2016 to 2018). "Moreover, oral supplementation of LSM to short bowel syndrome rats recovering from intestinal resection, reduced mucosal and systemic inflammation as shown by reduced concentrations of endotoxin in the serum and lowered pro-inflammatory cytokines (IL-6 and TNF-α) in the intestinal tissue." (PMID 30042761, 2018).